NLRP3 (NLR family pyrin domain containing 3)
Diseases named in the same sentence as NLRP3 in open-access papers (continued):
Sharing a sentence is not in itself a finding about the gene and the disease.
COVID-19 (continued). "Evidence supporting the role of AhR in lung physiology, including negative NLRP3 regulation, could provide new COVID-19 therapeutic opportunities based on the AhR and/or other xenobiotic receptor biological functions." (PMID 33916409, 2021). "This manuscript highlights the importance of NLRP3 inflammasome in the pathogenesis of nCoVs, discusses its known inhibitors and draws attention toward evaluation of these and similar known or novel agents for potential beneficial effects in the treatment of SARS-CoV-2 (COVID-19)." (PMID 32574259, 2020). "Finally, new therapies based on avoiding NETosis, blocking inflammation mediated by NLRP3 inflammasome, or blocking the pathway activated through L-SIGN, could also be feasible strategies to improve critical characteristics related to COVID-19." (PMID 33003552, 2020). "Heterogeneous response of COVID-19 patients could be attributed to differences in not being able to properly downregulate NLRP3 inflammasome activation." (PMID 32670297, 2020). "Indeed, NLRP3 and caspase 1 expression were not significantly different from COVID-19 lungs." (PMID 35144622, 2022). "In addition, an elegant study has recently shown that S protein signals through TLR2 and activates the NLRP3 (NLR family pyrin domain containing 3) inflammasome in human macrophages obtained from convalescent patients with COVID-19, but not from healthy SARS-CoV-2–naïve individuals." (PMID 36112681, 2022). "Considering that the deregulation of TLRs and NLRP3 is closely related to the severity of SARS-CoV-2 pathology, it can be assumed that glycosyl flavonoids could exert significant antiviral and immunomodulatory effects mediated through TLRs or NLRP3 inflammasomes in COVID-19 patients." (PMID 34200456, 2021). "Besides, activation of NLRP3 (nucleotide-binding domain, leucine-rich-containing family, pyrin domain-containing-3) inflammatory bodies is lacking in bats, so the use of NLRP3 inhibitor MCC950 may be helpful in the treatment of COVID-19." (PMID 33133232, 2020). "For instance, IL1B, NFKB1, NLRP3, PYCARD, and CASP1 are listed in the COVID-19 Disease Map, while there are molecules absent from it, including CCL3, 3L1, 4L2, CXCL1, 2, 3, 5, 16, TNFAIP6, C15orf48, TMEM176A/B, NFE2, PADI4, RAB20, ETS2, PHLDA2, FOLR3, and HP." (PMID 37719701, 2023). "Taken together, our data show that NLRP3 inflammasome pathway activation was not different between COVID-19 and non-COVID-19 ARDS suggesting that this pathway is not COVID-19 specific and is possibly more related to respiratory distress." (PMID 35144622, 2022). "Thus, it seems that the inhibition of NLRP3 inflammasome activation and effects may point towards a better understanding of the molecular mechanism that can be further explored in post-ischemic stroke (with or without COVID-19) brain repair." (PMID 35328506, 2022). "COVID-19 patients suffered from headache had significantly higher serum levels of HMGB1, NLRP3, ACE2, and IL-6 than COVID-19 patients without headache, whereas CGRP and IL-10 levels were similar in the groups." (PMID 34384355, 2021). "COVID-19 patients with headache had significantly higher serum levels of HMGB1, NLRP3, ACE2, and IL-6 than COVID-19 patients without headache, whereas CGRP and IL-10 levels were similar." (PMID 34794375, 2021). "Taken all the data together, we found significant elevations of circulating HMGB1, NLRP3 and IL6 levels in COVID-19 patients with headache compared to COVID-19 patients without headache." (PMID 34384355, 2021). "Compared to COVID − 19 patients without headache, serum levels of HMGB1, NLRP3, IL-6, angiotensin II, and ACE2 were significantly higher in COVID-19 patients with severe headache." (PMID 34384355, 2021). "A small, randomized trial of patients with COVID-19 demonstrated the ability of colchicine, which indirectly inhibits the NLRP3 inflammasome, to reduce the requirement of oxygen, though current NIH guidelines do not recommend colchicine for the treatment of COVID-19." (PMID 36419185, 2022).
COVID-19 (continued). "While previous studies suggest that DA can supress NLRP3, leucine-rich repeat (LRR), and pyrin domain-containing protein 3 (NLRP3) inflammasome activation via DRD1 pathways, our findings indicate that DRD4 may not mediate this mechanism in the context of post-COVID-19 recovery." (PMID 41574058, 2025).
type 2 diabetes (370 papers, 2011 to 2026). "Glyburide has been shown to block NLRP3 inflammasome activity and IL-1β secretion stimulated by islet amyloid polypeptide, which is associated with type 2 diabetes." (PMID 38892264, 2024). "In the spinal cord, the NLRP3/Casp1/IL-1β inflammasome activation axis is associated with chronic itch in type 2 diabetes and IMQ-induced chronic itch models." (PMID 39867900, 2024). "It is important to note that the development of type 2 diabetes, mitochondrial dysfunction, and insulin resistance are strongly associated with NLRP3 inflammasome activation, which are major risk factors for developing NASH." (PMID 37805545, 2023). "Persistent and aberrant NLRP3 signaling underlies many chronic diseases, including type 1 and type 2 diabetes, while NLRP3 deficiency has been shown to protect against injury, irrespective of the renal cell type." (PMID 36429063, 2022). "The NLRP3 inflammasome is associated with various disease formations including Alzheimer’s disease and atherosclerosis as well as type 2 diabetes." (PMID 35566202, 2022). "MPTP treatment in a type 2 diabetes (T2D) model increases raises the levels of α-synOs in both pancreas and midbrain, resulting in IL-1β secretion via NLRP3 activation, and ultimately exacerbates the loss of DA neurons." (PMID 36081661, 2022). "In other in vivo settings of arthritis, cryopyrin-associated periodic syndrome (CAPS), and type 2 diabetes, tranilast prevented NLRP3-dependent inflammatory effects by directly binding to the NATCH domain of NLRP3." (PMID 35204152, 2022). "Associations between genetic polymorphisms in the NLRP3 gene and the development of insulin resistance and type 2 diabetes have also been described, which indicates its pathogenetic relevance." (PMID 35931812, 2022). "In recent years, NLRP3 inflammasome has been identified as a crucial component of the mechanism underlying the development of systemic inflammation and progression of type 2 diabetes." (PMID 34943988, 2021). "One of the hallmarks of this disorder is a high inflammation rate and it has been shown that the NLRP3 inflammasome is deeply implicated in the development of insulin resistance in type 2 diabetes." (PMID 32650482, 2020). "NLRP3 rs10754558 polymorphism was reported as associated with type 2 diabetes in the Chinese population." (PMID 32545355, 2020). "It is widely known that NLRP3 inflammasomes are associated with the pathogenic mechanisms of type 2 diabetes and its associated complications." (PMID 32842536, 2020). "In conclusion, our study shows an association between vascular dysfunction in type 2 diabetes, and NLRP3 inflammasome and MR receptor activation." (PMID 31817997, 2019). "Another study indicated that decrease in NLRP3 expression in adipose tissue is associated with reduction in inflammation and improvement of insulin-sensitivity in type 2 diabetes with obese patients." (PMID 31088900, 2019). "Consistent with this, NLRP3 deficiency or IL-1 inhibition is beneficial in mouse models of these diseases and type 2 diabetic patients treated with anti-IL-1 therapy display improvements in glucose control and markers of systemic inflammation." (PMID 29515457, 2018). "The NLRP3 inflammasome, as a vital component of the innate immune system, is implicated in the pathogenesis of type 2 diabetes." (PMID 29230270, 2017). "NLRP3 inflammasome levels also correlate with glycaemia in type 2 diabetes patients after weight loss interventions." (PMID 23843683, 2013). "Like Compound CY-09, Tranilast could be a potential pharmacological approach for the prevention/treatment of NLRP3-driven diseases such as type 2 diabetes, gouty arthritis, and cryopyrin-associated auto-inflammatory syndrome." (PMID 40643515, 2025). "Furthermore, NLRP3 activated by islet amyloid polypeptide aggregates has been implicated to be associated with type 2- diabetes." (PMID 40643515, 2025).
type 2 diabetes (continued). "Increased NLRP3 inflammasome activity also accelerates up the development of several inflammatory conditions, such as cryopyrin-associated periodic syndrome, arthritis, atherosclerosis, type 2 diabetes, Alzheimer’s disease, and cancers." (PMID 37715239, 2023). "A growing number of studies have demonstrated that many risk factors for type 2 diabetes, such as high glucose and high fat, can activate the NLRP3 inflammasome in endothelial cells (ECs) and macrophages to mediate pyroptosis and exacerbate the progression of AS." (PMID 36387904, 2022). "Emerging evidence has indicated that the activation of the NLRP3 inflammasome might lead to the maturation and secretion of IL-1β, which has been implicated in the pathological development of type 2 diabetes and cardiovascular diseases." (PMID 34576117, 2021). "The implication of the innate immune system by specific activation of NLRP3 inflammasome pathway is more and more discussed as the pathogenic background of type II diabetes mellitus (T2D), and CMS and its involvement in the therapeutic field changed the paradigm of CMS treatment." (PMID 33172097, 2020). "However, some researchers have found that FS is associated with an increased incidence of type 2 diabetes, impairs insulin signaling, and worsens insulin resistance, inducing inflammatory responses by the NLRP3/caspase-1 pathway." (PMID 30939798, 2019). "Other studies have revealed that excessive NLRP3 activation is implicated in diseases driven by metabolic dysfunction such as type 2 diabetes and nonalcoholic steatohepatitis, in neurodegenerative diseases including Alzheimer’s disease and Parkinson’s disease, and in cancer." (PMID 31590215, 2019). "Recent advances also reveal that NLRP3 inflammasome can act like a metabolic sensor in response to metabolic alterations in cells, and its activation is associated with several metabolic disorders, such as type 2 diabetes and obesity." (PMID 26847702, 2016). "To test this hypothesis, we treated vascular endothelial cells and rats with simvastatin in diabetic condition and observed the NLRP3 inflammasome and changes of vascular permeability which is a common pathogenic change during the development of chronic inflammation such as type 2 diabetes." (PMID 29207644, 2017). "NLRP3 rs1539019 is an intronic polymorphism whose function is less intuitive, whereas, recent studies have reported that intronic polymorphisms are associated with a variety of chronic diseases such as breast cancer, type II diabetes and essential hypertension." (PMID 23110140, 2012). "The aim of this review is to assess the role of the NLRP3 inflammasome in the pathogenesis of type 2 diabetes, as well as the potential of inflammasome pathway inhibitors as promising therapeutic agents." (PMID 41640166, 2026). "In patients with poorly controlled type 2 diabetes, those with chronic periodontitis displayed higher caspase-1 mRNA levels and elevated protein levels of NLRP3, ASC, and IL-1β compared with periodontitis patients who were not diabetic." (PMID 41440367, 2025). "In type II diabetes, mitochondrial ROS accumulation activates the NLRP3 inflammasome, which then triggers the Caspase-1/GSDMD pathway and initiates pyroptosis in muscle cells." (PMID 41334559, 2025). "Either AGE, HMGB1, S100, or mtDNA induce AIM2 or NLRP3 inflammasome activation which plays a critical role in the pathogenesis of type 2 diabetes." (PMID 40216765, 2025). "It was shown that SGLT2 inhibitors decrease the levels of proinflammatory cytokines in patients with type 2 diabetes, as well as the activity of NLRP3 inflammasome." (PMID 40004134, 2025). "As for the NLRP3 inflammasome, it is of special interest because some preliminary evidence suggests that NLRP3 may serve as an independent predictor of disease risk during the subclinical stages of inflammatory conditions such as periodontitis and type II diabetes mellitus." (PMID 41462866, 2025).
type 2 diabetes (continued). "NEK7, encoding NIMA-related kinase 7, is a crucial factor involved in chronic immune inflammation in type 2 diabetes by triggering the activation of the NLRP3 inflammasome complex." (PMID 41465472, 2025). "Evidence shows that NLRP3 plays a role in glucose tolerance, insulin resistance, and inflammation in both type 1 and type 2 diabetes." (PMID 41440367, 2025). "EGCGwas reported to have renoprotective effects on type 2 diabetic rats mainly via repression of endoplasmic reticulum stress-mediated NLRP3 inflammasome." (PMID 39795863, 2024). "Engaging in aerobic exercise can improve IR and reduce the expression of NLRP3 and IL-1β in individuals with type 2 diabetes in aortic tissue, suggesting its positive impact on IR by inhibiting NLRP3 inflammasome." (PMID 38681198, 2024). "The various modes of activating the NLRP3 inflammasome are fundamental factors influencing its complex effects on the progression of type 2 diabetes." (PMID 38681198, 2024). "In the development of Type 2 diabetes, elevated insulin levels increase ROS levels, activate NLRP3 inflammasomes, and trigger subsequent inflammatory responses." (PMID 39619569, 2024). "For example, miR-224-5p lessens microglial inflammation by regulating NLRP3 to influence the progression of obstructive sleep apnea and type 2 diabetes." (PMID 38455868, 2024). "NLRP3 knockout mice exhibited suppression of diabetic nephropathy in both type 1 and type 2 diabetes by blocking NLRP3-mediated mitochondrial ROS generation." (PMID 38740765, 2024). "CY-09 directly targets NLRP3, inhibiting its inflammasome activation in vivo, and has shown significant therapeutic effects in mouse models of NLRP3-driven diseases, such as type 2 diabetes and CAPS." (PMID 39131161, 2024). "Logistic regression analysis revealed that NLRP3 and MALAT1 were independent risk factors for LEAD in patients with type 2 diabetes." (PMID 38439031, 2024). "The results showed that age, smoking, SBP, NLRP3, and MALAT1 were independent risk factors for LEAD in patients with type 2 diabetes (P < 0.05)." (PMID 38439031, 2024). "The third article, published by Hye-Mi Lee in 2013, is titled “Upregulated NLRP3 Inflammasome Activation in Patients with Type 2 Diabetes”." (PMID 39717099, 2024). "Peripheral blood-derived macrophages from drug-naïve patients with type 2 diabetes show increased expression of NLRP3 and ASC along with caspase-1 activation and IL-1β maturation." (PMID 38681198, 2024). "Oridonin exerts therapeutic effects on gouty arthritis, peritonitis, and type 2 diabetes in an NLRP3 inflammasome-dependent manner." (PMID 37915104, 2023). "The NLRP3 inflammasome has been linked to the etiology of several inflammatory and metabolic diseases, including MAFLD and type 2 diabetes." (PMID 36670488, 2023). "For example, ω-3 fatty acids can alleviate high-fat food-induced type 2 diabetes by inhibiting NLRP3 inflammatory vesicles and reducing the secretion of IL-1b, a key factor in inflammation." (PMID 37047050, 2023). "Clinical studies have shown that the NLRP3 pathway is significantly activated and the levels of Caspase1 and IL-1β are significantly increased in obese and type 2 diabetes patients compared to healthy subjects." (PMID 36834674, 2023). "Although the exact pathogenesis of PDN is unclear, there was increased secretion of mRNA encoding NLRP3, ASC, IL-1β, and IL-18 in macrophages and peripheral blood monocytes of patients with type 2 diabetes mellitus." (PMID 37106238, 2023). "A study on animals found that mice fed a hypercaloric diet acquired airway hyperreactivity that was dependent on NLRP3 but unrelated to adaptive immunity (just as it appears to regulate type 2 diabetes)." (PMID 38022144, 2023). "Recent studies have shown the potential therapeutic role of the NLRP3 inflammasome/pyroptosis signaling pathway in type 2 diabetes and its complications." (PMID 36387904, 2022).